MIR1-1HG (MIR1-1 host gene)
Synonyms: C20orf166; dJ353C17.1; MIR133A2HG
Gene: Long non-coding RNA gene on chromosome 20 (62,550,440 to 62,570,777, forward strand). Ensembl gene ENSG00000174407.
Gene Ontology:
Biological process: miRNA-mediated post-transcriptional gene silencing
Cellular component: RISC complex